HLA-G (major histocompatibility complex, class I, G)
Diseases named in the same sentence as HLA-G in open-access papers (continued):
Sharing a sentence is not in itself a finding about the gene and the disease.
rectal cancer (10 papers, 2014 to 2025). A primary or metastatic malignant neoplasm that affects the rectum. "The expression of HLA-G in colon cancer or rectal cancer was higher than that in corresponding normal tissues, yet the difference was not significant." (PMID 37875821, 2023). "However, it is interesting to note that in ovarian and rectal cancers, HLA-G expression is associated with a good prognosis, suggesting that HLA-G is not only involved in the regulation of anti-tumor immunity, but its expression may also reflect genome integrity." (PMID 36253800, 2022). "Overall, 70.7% (323/457) of primary CRC samples were HLA-G positive, which was positive in 76.7% of the colon (178/232) and 64.4% of the rectal carcinoma lesions (145/225), respectively." (PMID 29296176, 2017). "In addition, activated CD8+ T cells, MDSCs and Tregs were expanded with increasing expression levels of HLA-G in colon cancer and rectal cancer." (PMID 37875821, 2023). "Specifically, HLA-G detection by IHC using 4H84 and MEM-G/1 were similarly consistent in placental tissues used as positive controls, but the staining in rectal cancer tissue was inconsistent and in conflict with the Western immunoblot analysis." (PMID 36671682, 2023). "No notable differences were found in CRC survival in terms of patient age, sex, pT stage, colon or rectal cancer types, and patients with low or high levels of HLA-G:ILT-2, and HLA-G:PD-L1 expression." (PMID 34054869, 2021). "The bioinformatic results showed that there was a nonsignificant difference, even though HLA-G expression in colon cancer or rectal cancer was higher than that in their corresponding normal tissues." (PMID 37875821, 2023). "The study with the highest proportion of patients with HLA-G positive tumours did not stratify patients in colon and rectal cancer cohorts." (PMID 35027037, 2022). "Recently, Kuppen and colleagues found that absence of HLA-G expression indicated a better survival for colon cancer patients and weak expression of HLA-G revealed a worse survival in rectal cancer patients." (PMID 29296176, 2017). "A similar lack of concordance was noted in the detection of HLA-G in rectal cancer tissue." (PMID 36671682, 2023). "As a result, high HLA-G expression was significantly linked to shorter OS in CRC patients (HR = 1.46, 95% CI = 1.17–1.81, P = 0.001) and colon cancer patients (HR = 1.39, 95% CI = 1.04–1.86, P = 0.028) but not in patients with rectal cancer (HR = 0.88, 95% CI = 0.66–1.18, P = 0.418)." (PMID 37875821, 2023). "However, no marked difference was found between the HLA-G, ILT-2, ILT-4 and PD-L1 expression status and the clinicopathological parameters, such as patient age, sex, and colon or rectal cancer types." (PMID 34054869, 2021).
type 1 diabetes (10 papers, 2014 to 2023). "Homozygosity for the deletion of 14 bp of the 3′ untranslated region of HLA-G was associated with an earlier age of type 1 diabetes onset, whereas heterozygotes (carrying only one deletion) had a later age of onset of type 1 diabetes." (PMID 31820163, 2019). "The upregulation in the expression levels of HLA-E, HLA-F and HLA-G in insulin-containing islets of patients with type 1 diabetes could conceivably be linked to a viral infection where the virus is attempting to shield itself from the immune system." (PMID 31820163, 2019). "de Albuquerque and coworkers have analyzed different polymorphism of 3′UTR of HLA-G gene in type 1 diabetes mellitus (T1D) patients." (PMID 27652273, 2016). "Some of the HLA-G gene polymorphisms and molecule levels have also been correlated with Type 1 Diabetes mellitus (T1D), a chronic and genetically complex disease characterized by pancreatic beta-cell destruction, mediated by humoral and cellular immune responses." (PMID 35154112, 2022). "In pancreas tissue from patients with recent-onset type 1 diabetes, upregulation of HLA-G at the protein level can be seen in the islets, in both α and β cells." (PMID 31820163, 2019). "This review focuses on the current understanding of the non-classical HLA-I subtypes: HLA-E, HLA-F and HLA-G, within and outside the field of type 1 diabetes, and considers the possible impacts of these molecules on disease etiology." (PMID 31820163, 2019).
colon carcinoma (9 papers, 2014 to 2025). "Nevertheless, the data of the 211528_x_at probe showed that high expression of HLA-G was associated with better OS in patients with colon cancer (HR = 0.79, 95% CI = 0.64–0.96, P = 0.02)." (PMID 37875821, 2023). "In the Kaplan-Meier Plotter, the data of the 210514_x_at probe was consistent with our results, while it could be seen that high expression of HLA-G was significantly associated with better OS in colon cancer patients from the 211528_x_at probe." (PMID 37875821, 2023). "In 201 colon cancer patients, IHC staining shows that the survival time of patients with HLA-G-positive tumors is significantly shorter compared with those carrying HLA-G-negative tumors." (PMID 34868081, 2021). "In this study, we explored the expression of prognostic markers in patients with pT3 and pT4 colon cancers including HLA-G and PD-L1, two markers of immune evasion, as well as the expression of CDX2, a marker of differentiation, and CD3 and CD8, markers of TILs." (PMID 35027037, 2022). "HLA-G expression above HLA-GHigh level showed a worse prognosis for female (p = 0.013), elder (p = 0.023), colon cancer (p = 0.016), advanced tumor burden (T3+4, p = 0.018), regional lymph node status (N1+2, p = 0.044), and advanced clinical stage patients (AJCC III+IV, p = 0.037)." (PMID 29296176, 2017). "Recently, however, it was shown that not only the absence of HLA-G and -E expression but also the absence of HLA class I expression was associated with worse survival in colon cancer patients." (PMID 24987709, 2014). "In conclusion, we investigated HLA-G, PD-L1, CDX2, and CD3 and CD8 as prognostic markers in patients with pT3 and pT4 colon cancers." (PMID 35027037, 2022). "In 81 patients with colon cancer, Swets and colleagues have used three monoclonal antibodies (4H84, MEM-G/1, and MEM-G/2) to evaluate the expression of HLA-G." (PMID 34868081, 2021). "The aim of this study was to explore the expression patterns of HLA-G, PD-L1, and CDX2 as well as CD3 and CD8 in a cohort of patients diagnosed with pT3 and pT4 colon cancers, and to investigate their value as prognostic markers individually and in a combined model." (PMID 35027037, 2022). "Among female patients, the elder patients, colon carcinoma patients, stage of T3+4, N1+2, and stage III+IV whose HLA-G expression above the cut-off 55% (HLA-GHigh) have dramatically poor survival than those with lower HLA-G expression." (PMID 29296176, 2017). "Surprisingly, the percentage of HLA-G surface-expressing B cells was not different between PDAC and colon cancer patients." (PMID 38022530, 2023).
lymphoma (9 papers, 2018 to 2026). A malignant (clonal) proliferation of B- lymphocytes or T- lymphocytes which involves the lymph nodes, bone marrow and/or extranodal sites. "Risk haplotypes have been identified for human non-Hodgkin’s lymphoma at HLA-A, -B, and -C, and lower expression levels of HLA-G have been associated with aggressive lymphoma and poor prognosis." (PMID 37756103, 2023). "In lymphomas, HLA-G has been explored in only few studies so far and the results regarding the predictive role of HLA-G expression are still equivocal." (PMID 29564225, 2018). "Notably, HLA-G expression in lymphoma is a double-edged sword with protective and destructive effects." (PMID 39020411, 2024). "The serum level of soluble HLA-G increased in NLHs such as DLBCL, FL, and peripheral T-cell lymphoma, which may disrupt NK cell function and be involved in lymphoma development." (PMID 39020411, 2024). "Similarly, in immune competent Balb/c mice, Fon lymphoma xenograft HLA-G expression, purportedly acting through the LILRB ortholog PIRB, conferred engraftment advantage over HLA-G- lymphoma." (PMID 39696628, 2024).
neuroblastoma (9 papers, 2012 to 2025). Neuroblastoma (NB) is the most common solid, extracranial childhood tumor. "In human solid tumors, HLA-G was found to be expressed in a wide variety of tumor cells such as colorectal, renal, lung, melanoma, pancreatic, hepatocellular, breast cancer, gastric carcinomas, and neuroblastoma." (PMID 35328349, 2022). "Alternatively, HLA-G may be limited to shed or secreted isoforms not expressed on the tumor cell surface, as shown in neuroblastoma." (PMID 29464090, 2018). "The role of nonclassical HLA-class Ib molecules HLA-G and HLA-E in the progression of Neuroblastoma (NB), the most common pediatric extracranial solid tumor, has been characterized in the last years." (PMID 27610393, 2016).
squamous cell carcinoma (9 papers, 2014 to 2025). A carcinoma arising from squamous epithelial cells. "HLA-G was also found in skin cancers, such as cutaneous lymphoma and skin basal and squamous cell carcinoma." (PMID 34201301, 2021). "Because the human tumor cell lines that we analyzed weakly expressed surface HLA‐E, we transfected the squamous cell carcinoma CAL‐27 cell line, whose expression of HLA‐E was at baseline around 20%, with a plasmid encoding the HLA‐E plus the HLA‐G signal peptide to achieve HLA‐E surface expression." (PMID 37782273, 2023). "interestingly showed a predominant expression of soluble HLA-G (sHLA-G) in tumor cells not from squamous cell carcinoma but adenocarcinoma of lung." (PMID 38450191, 2024).
Crohn disease (8 papers, 2010 to 2025). A gastrointestinal disorder characterized by chronic inflammation involving all layers of the intestinal wall, noncaseating granulomas affecting the intestinal wall and regional lymph nodes, and transmural fibrosis. "As HLA-G 14-bp Ins/Del polymorphism is associated with mRNA stability and soluble HLA-G level, the polymorphism has been studied extensively in various diseases such as diabetes mellitus, Crohn’s disease, cancer, and celiac disease." (PMID 34684043, 2021). "It has been reported that genetic variants with a 14-bp deletion polymorphism in the HLA-G region are associated with Kawasaki disease, juvenile idiopathic arthritis, ulcerative colitis, and Crohn's disease." (PMID 20573271, 2010). "The immunosuppressant therapy normalizes the production of HLA-G molecules in Crohn’s disease while it starts the release of HLA-G in UC patients." (PMID 25477881, 2014). "The different HLA-G expression profiles in UC and Crohn’s disease patients sustain the different aethiopathogenesis at the origin of these two diseases." (PMID 25477881, 2014).
diabetes (8 papers, 2014 to 2025). "In studies concerning the HLA-G polymorphisms, it has been shown that HLA-G polymorphism can act as a risk factor for diabetes mellitus in both kidney and pancreas transplantation." (PMID 35769475, 2022). "Their research was based on the analysis of the relationship between the HLA-G molecule and the metabolic and inflammatory pattern found in obesity and diabetes, and the varying degrees of glucose tolerance in these patients." (PMID 34948145, 2021). "Otherwise, HLA-G contributes to the trend towards the Th2 phenotype, acting as a counterbalance to the characteristic inflammatory response of both types of diabetes; however their pathophysiological mechanisms are different." (PMID 24689061, 2014). "In some studies however, the relation with graft acceptance was not so clear and in these studies expression of HLA-G was determined by time after transplantation, inflammatory processes, or specific genotypes associated with diabetes." (PMID 35769475, 2022). "In this study, we have shown that HLA-G in normal pregnant women is higher than pregnant women with diabetes, this could be related to the activity of these molecules in regulating the immune system." (PMID 27757202, 2016). "On the basis of these data, it could be hypothesized that an impaired HLA-G expression at pancreatic islets could sustain T cell activation and onset of diabetes." (PMID 25477881, 2014).
HIV-1 infection (8 papers, 2006 to 2021). The type species of lentivirus and the etiologic agent of acquired immunodeficiency syndrome (AIDS). "HLA-G*01:01:08 was reported to be a risk factor for HIV-1 infection in Zimbabwean while 3’UTR 14-bp In/14-bp In was a risk factor for HIV infection in South Africans of African ancestry women." (PMID 34938296, 2021). "Although HLA-G polymorphisms are limited, certain HLA-G alleles have been suggested to be involved in susceptibility to HIV-1 infection." (PMID 29184550, 2017). "Other HLA-G alleles identified were HLA-G*01:04:04, which associated with susceptibility to HIV-1 infection, and HLA-G*01:01:01, which was enriched in HIV-1–resistant women." (PMID 29184550, 2017). "We observed that HLA-G+ CD4 Treg were significantly more susceptible to HIV-1 infection than autologous HLA-G− CD4 T cells; this was true both for in vitro activated cells and for cells directly infected ex-vivo." (PMID 23382678, 2013). "We next investigated whether the reduced frequencies of circulating HLA-G+ Treg during progressive HIV-1 infection are associated with an altered phenotypic differentiation or maturation status." (PMID 23382678, 2013). "The reduction of HLA-G+ CD4 Treg during progressive HIV-1 infection may be related to their increased susceptibility to HIV-1 infection, which is likely due to enhanced expression of the viral co-receptors CCR5 and CXCR4 demonstrated in this study." (PMID 23382678, 2013). "This selective loss of HLA-G+ Treg during advanced HIV-1 infection may, in conjunction with other mechanisms, contribute to immune overactivation during progressive HIV-1 infection." (PMID 23382678, 2013). "Our results indicate a profound reduction of HLA-G+ CD4 Treg in individuals with progressive HIV-1 disease that may stem from a higher susceptibility of these cells to HIV-1 infection, and functionally contribute to HIV-1-associated immune overactivation." (PMID 23382678, 2013). "The aim of this study was to investigate whether soluble HLA-G (sHLA-G) expression in the female genital tract is associated with HIV-1 infection." (PMID 21966450, 2011). "However, initial exposure to HIV-1 during sexual transmission occurs in the female genital tract and no data are available on the possible association between genital HLA-G expression and susceptibility to HIV-1 infection." (PMID 21966450, 2011). "The immunosuppressive properties of HLA-G might contribute to the susceptibility to HIV-1 infection." (PMID 21966450, 2011). "However, association of this HLA-G gene with HIV-1 infection or transmission is yet to be fully determined." (PMID 17059603, 2006). "Moreover, soluble HLA-G could inhibit myeloid dendritic cell function, and higher peripheral circulating sHLA-G levels were shown to be linked to the rapid progression of HIV-1 infection." (PMID 34938296, 2021). "In addition, the specific reason for the loss of HLA-G+ CD8 Treg in untreated progressive HIV-1 infection remains unclear and warrants further investigation." (PMID 23382678, 2013). "Only a low percentage of immune cells in healthy subjects expresses HLA-G, whereas in HIV-1 infection a substantial upregulation of HLA-G has been observed in both peripheral blood monocytes and T-cell subsets." (PMID 29184550, 2017). "Moreover, they hypothesized that the association between HLA-G*0105N and the increased risk of HIV-1 infection was caused by the capacity of the null allele, when present, to increase the production of other HLA-G isoforms, thus compensating the absence of HLA-G1 and -G5 and inhibiting the NK lysis." (PMID 23841087, 2013). "This work demonstrates that in contrast to classical Treg, HLA-G-expressing Treg progressively decline during advanced HIV-1 infection." (PMID 23382678, 2013). "To investigate this, we analyzed the susceptibility of HLA-G+ CD4 Treg to X4- or R5-tropic HIV-1 viruses, or to a VSV-G-pseudotyped HIV-1 construct causing single-round HIV-1 infection." (PMID 23382678, 2013).
HIV-1 infection (continued). "Here, we show that non-classical HLA-G-expressing CD4 Treg are highly susceptible to HIV-1 infection and significantly reduced in persons with progressive HIV-1 disease courses." (PMID 23382678, 2013). "Since HLA-G+ Treg express multiple tissue homing factors, a redistribution of these cells to lymphoid tissues may be responsible for the apparent reduction of HLA-G-expressing Treg in the peripheral blood during progressive HIV-1 infection." (PMID 23382678, 2013). "Overall, these data suggest that HLA-G-expressing Treg may contribute to balancing and fine-tuning anti-viral immune activity and bystander immune activation during HIV-1 infection." (PMID 23382678, 2013). "Direct HIV-1 infection of HLA-G+ CD4 Treg may contribute to the reduction of these cells in progressive HIV-1 infection." (PMID 23382678, 2013). "In this way, HLA-G-expressing Treg may represent a previously unrecognized barrier against HIV-1 associated immune activation and a possible target for future immunotherapeutic interventions in HIV-1 infection." (PMID 23382678, 2013). "Based on these results, it is increasingly clear that HLA-G variants in exon 8-UTR, either alone or in combination with exon 2 codon 57 that was previously reported and the 5' UTR could influence the risk of MTCT of HIV-1 infection." (PMID 17059603, 2006). "Thus, data on sHLA-G levels in HIV-1 infection need to be carefully controlled for confounding factors such as HAART, HLA-G genetic background, sampling site, or coinfections." (PMID 29184550, 2017). "Here, we demonstrate several numerical and functional aspects of non-classical HLA-G-expressing Treg in HIV-1 infection that clearly distinguish them from these recognized characteristics of classical Treg." (PMID 23382678, 2013). "Overall, these data indicate that during HIV-1 infection, HLA-G-expressing CD8, but not CD4 T cells, are skewed to a more immature differentiation status, but this difference is not correlated to the rates of spontaneous HIV-1 disease progression." (PMID 23382678, 2013). "Furthermore, expression of several other molecules is increased on monocytes after HIV-1 infection, e.g. CD23, CD36, CD14, CD126, HLA-G, and sialoadhesin (and this study)." (PMID 17330143, 2007). "Yet, due to the numeric reduction of HLA-G+ Treg in progressive HIV-1 infection, all functional effects of these cells could not be evaluated using cells from this particular patient population." (PMID 23382678, 2013).
non-small cell lung carcinoma (8 papers, 2016 to 2024). A group of at least three distinct histological types of lung cancer, including non-small cell squamous cell carcinoma, adenocarcinoma, and large cell carcinoma. "The purpose of this study was to investigate the influence of HLA-G allelic variants and serum soluble HLA-G (sHLA-G) levels on risk of non-small-cell lung cancer (NSCLC)." (PMID 27517300, 2016). "For example, in non-small cell lung carcinoma (NSCLC), a loss of classical HLA class I antigens was found to be associated with an upregulation of HLA-G as well as IL-10 expression." (PMID 35185904, 2022). "In non-small cell lung cancer (NSCLC), HLA-G and PD-L1 expression were boosted in a dose-dependent manner by several chemotherapeutic agents, among which pemetrexed promoted the glycosylation of HLA-G and PD-L1 consistently as a belt-and-braces approach to the tumor cell immune escape." (PMID 38310272, 2024).